RN7SKP7 (RN7SK pseudogene 7)
Gene: Miscellaneous RNA gene on chromosome 13 (96,949,249 to 96,949,533, reverse strand). Ensembl gene ENSG00000222472.
Homologues: Orthologues: chimpanzee 7SK (99% identical), mouse Gm54931 (62% identical). Paralogues in human: 7SK (74% identical), RN7SKP176 (73% identical), RN7SKP203 (73% identical), RN7SKP217 (72% identical), RN7SKP71 (72% identical), RN7SKP255 (72% identical), RN7SKP9 (72% identical), RN7SKP124 (71% identical), RN7SKP193 (71% identical), RN7SKP90 (71% identical), RN7SKP80 (71% identical), RN7SKP186 (70% identical), and 284 more.